EGF (epidermal growth factor)
Diseases named in the same sentence as EGF in open-access papers (continued):
Sharing a sentence is not in itself a finding about the gene and the disease.
breast carcinoma (continued). "In addition, EGF-induced EMT in MDA-MB-468 breast cancer cells has been linked to altered plasma membrane calcium influx." (PMID 23890218, 2013). "In this study we assessed whether alterations in mRNA levels of Golgi, mitochondrial and ER calcium channels, pumps and exchangers were associated with EGF-induced EMT in MDA-MB-468 breast cancer cells." (PMID 23890218, 2013). "Furthermore, EGF-secreting macrophages were shown to be recruited to tumor-associated blood vessels that secrete SDF-1α from pericytes in a rat breast cancer model." (PMID 23869217, 2013). "Additionally, treatment of unmodified breast cancer cells (or cells expressing only WT PR-B) with EGF further implicated PR Ser294 phosphorylation (PR deSUMOylation) in transcriptional derepression of selected PR target genes." (PMID 22697792, 2012). "In conclusion, the induction of EMT by EGF in MDA-MB-468 breast cancer cells is associated with alterations in the calcium signaling response to ATP and results in a cellular phenotype with an altered transcriptional profile of purinergic receptors, in particular an upregulation of P2X5." (PMID 21850275, 2011). "In this study, we investigated whether Rac1/ROS regulates PI3K/Akt and PAK1 signaling and is critically linked to EGF-mediated breast cancer cell migration." (PMID 23554696, 2011). "A lower risk for breast cancer in G/G carriers might be explained through EGF receptor internalization promoted by EGF." (PMID 20487573, 2010). "Involvement of EGF signalling in the pathogenesis of bone metastasis was implicated by the unexpected relief of bone pain in phase II clinical trials of EGFR inhibitor gefitinib in breast cancer patients." (PMID 20010942, 2010). "Further research will elucidate whether certain tumour types are more or less susceptible to anti-VEGF/EGF strategies, and breast cancer may prove to be a tumour type that is difficult to treat with this approach." (PMID 15928653, 2005). "The higher levels of Cath-D and EGF/alpha-TGF found in apocrine cysts could provide an explanation for the increased risk of subsequent breast cancer in women with this type of cyst." (PMID 1931627, 1991). "The higher levels of EGF in cysts with low intracystic electrolyte ratios may provide an explanation of why women with apocrine cysts may be at greater risk of breast cancer." (PMID 2528985, 1989). "The upregulation of EGF, a key growth factor in this pathway, suggests that PCBs may promote tumor growth and progression by enhancing EGF receptor signaling, a mechanism previously linked to poor prognosis in breast cancer." (PMID 40584614, 2025). "For example, hollow gold nanoparticles can be used to detect marker-specific molecules of the human epidermal growth factor causing cancer, while SiO2-encapsulated hollow gold nanoparticles are capable of detecting marker-specific molecules of breast cancer cells and imaging breast cancer cells." (PMID 39269079, 2024). "In addition, RGS16 can inhibit the epidermal growth factor (EGF)-mediated proliferation of breast cancer cells; and it is also associated with lymph node metastasis of pancreatic cancer and may be a prognostic marker for pancreatic cancer." (PMID 29108247, 2017). "Variation in the ESR1 (MIM 133430) and EGF (MIM 131530) genes affecting the function or expression of their respective proteins could thus potentially affect the risk of developing breast cancer, characteristics of the tumour or the risk of dying from the disease." (PMID 18271972, 2008). "Here, we use mass spectrometry imaging (MSI) to measure glycerophospholipids at the single-cell level during EGF-induced EMT in MDA-MB-468 breast cancer cells." (PMID 42109846, 2026). "To assess the effects of EGF on breast cancer cell growth, we employed the PrestoBlueTM Cell Viability Assay, which specifically focuses on TNBC cell proliferation." (PMID 41188939, 2025).
breast carcinoma (continued). "Ferulic acid reduced breast cancer cell proliferation by inhibiting EGF activity and decreasing Tyr 1068 autophosphorylation in vitro." (PMID 40076243, 2025). "To determine if ambrosin inhibited EGFR phosphorylation, we stimulated serum-deprived bladder cancer and breast cancer cells with 10 nM EGF for 2 h to induce auto-phosphorylation of tyrosine 1068 (Y1068), a documented marker of EGFR activation." (PMID 40754248, 2025). "Consistently, TNS3 knockdown inhibited cell migration in MDA-MB-468 breast cancer cells, though interestingly in an EGF induction-dependent manner." (PMID 40906372, 2025). "Particularly, cross-talk between the calcium-sensing receptor and the EGFR in MCF-7 breast cancer cell proliferation has been observed, and cooperative signaling between calcium and EGF on tumor cells has also been observed." (PMID 39940827, 2025). "Meanwhile, the epidermal growth factor (EGF) stabilizes PD-L1 through GSK3b inactivation in basal-like breast cancer." (PMID 39958358, 2025). "MAS-R was highly expressed in the ER− compared to the ER+ breast cancer cells, and EGF stimulation further enhanced (by twofold) its expression in pII cells." (PMID 40149544, 2025). "Key pathways such as PI3K-Akt signaling, MAPK signaling, and breast cancer are linked with multiple targets including BRCA1, FGFR1, IGF1, AKT1, and EGF, suggesting their potential involvement in breast cancer pathology influenced by PCBs exposure." (PMID 40584614, 2025). "Glucose consumption is upregulated in EGFRvIII mutant U87 glioblastoma cells, and in breast cancer cells treated with EGF or that overexpress EGFR." (PMID 39433211, 2025). "The cullin-3/KCTD10 E3 ubiquitin ligase complex promotes RhoB degradation, and activates epidermal growth factor (EGF)/human epidermal growth factor receptor 2 (HER2)-dependent Rac1 signaling in HER2-positive breast cancer cells." (PMID 40873559, 2025). "Conversely, in breast cancer, it enhances the stability of the EGF mRNA and increases doxorubicin resistance in breast cancer cells, thus promoting chemoresistance." (PMID 40435202, 2025). "Epidermal growth factor (EGF) stabilizes PD-L1 through GSK3b inactivation in basal-like breast cancer." (PMID 39958358, 2025). "ELK1, but not SRF or STAT3, was reported to regulate both the basal and epidermal growth factor induced MCL1 transcription in breast cancer cells." (PMID 40075071, 2025). "RNA-Seq analysis of breast cancer cells treated with cSNX1.3 or modified to lack a nuclear localization sequence (EGFRΔNLS) revealed the EGF-dependent induction of NK activating receptor ligands, while kinase inhibition by erlotinib did not impact these genes." (PMID 39521886, 2025). "TGFβ and EGF are two of the primary growth factors that regulate invasion and metastasis of breast cancer tumors and promote EMT." (PMID 38760173, 2024). "Up to now, there are no data indicating the ability of CBG to reduce EGFR expression; however, some studies demonstrated that CBD and THC can reduce EGFR expression in A549, H460, and H1792 cells and suppress EGF/EGFR signaling pathways in breast cancer." (PMID 38396679, 2024). "For example, epidermal growth factor (EGF) is a protein that can be attached to the surface of AuNPs to target breast cancer cells that overexpress EGFR receptors." (PMID 39458661, 2024). "In these studies, it was determined that the CAIX expression level in breast cancer cells increased remarkably when EGF was applied." (PMID 39590368, 2024). "According to the literature, increased EGF expression was observed in 70–75% of established CRC cases, and EGFR was associated with various types of cancer, including CRC, breast cancer, and non-small cell lung cancer." (PMID 39063041, 2024). "LPs and BCs proliferate in vitro in the presence of EGF and are thought to be the origin of most triple-negative and poorly treatable human breast cancers." (PMID 38321033, 2024).
breast carcinoma (continued). "The cell experiments in our study also showed that MARCH1 mediated the TBK1-mTOR signaling pathway to both respond to insulin and EGF stimulation in breast cancer cells." (PMID 39061024, 2024). "MCF-7 cells, which are rich in breast cancer stem cells, were treated with EGF, after injection of sh-serpin E2 lentivirus into the tail vein of mice." (PMID 38469181, 2024). "We showed that the addition of EGF increases nuclear shuttling of CapG in the breast cancer cells MDA-MB-231 within minutes." (PMID 39369027, 2024). "While EGF is a prominent growth factor in breast cancer, it has been shown before, that a subset of breast cancer cells also respond to EGF with cell cycle arrest and apoptosis." (PMID 38187472, 2024). "At the proteomic and transcriptomic levels, we examined the changes in the HER2-positive breast cancer cell line SK-BR-3 profiles upon treatment with lapatinib, either alone or in combination with human serum or EGF." (PMID 39403185, 2024). "Promotion of invasion and migration of breast cancer cells by TAMs to distant sites by secreting EGF which binds to EGFR on breast cancer cells has been observed." (PMID 38703051, 2024). "It has been previously reported that EGF is able to induce MIF expression in MCF10CAT breast cancer cells as well as in A431 cervical cancer cells through EGFR/MEK/ERK1/2 signaling pathway." (PMID 38145300, 2024). "EGF has been a targeted molecule in breast cancer in women since 1998 (HER2), when the first anti-HER2 antibody, trastuzumab, was approved." (PMID 38256245, 2024). "Intriguingly, it is prevalent that EGF signaling is activated in many tumors such as lung cancers and breast cancers, and has shown to be important for aerobic glycolysis by regulating the glycolytic enzymes posttranslational modifications." (PMID 38750259, 2024). "The epidermal growth factor (EGF) family member amphiregulin (AREG) was identified 25 years ago in the supernatant of MCF-7 human breast carcinoma cells treated with phorbol 12-myristate 13-acetate (PMA)." (PMID 38394508, 2024). "Previous studies have shown that both EGF and TGFβ can be secreted by endothelial cells and induce the acquisition of a mesenchymal-like phenotype in breast cancer cells." (PMID 38762624, 2024). "Serum-starvation doubled the number of breast cancer cells from 40 to 80% displaying increased CapG shuttling in response to EGF." (PMID 39369027, 2024). "Invasive tumor cells and macrophages have been found to co-migrate in primary mammary tumors of mice and rats only in response to EGF and CSF-1; thus, blockade of either EGF receptor or CSF-1 receptor signaling blocks migration of both cell types in vivo." (PMID 39003350, 2024). "Estradiol was reported to enhance macrophage influx and angiogenesis by increasing the release of CCL2, CCL5, and EGF in estrogen-positive breast cancers." (PMID 39003350, 2024). "Trastuzumab, a monoclonal antibody that inhibits epidermal growth factor, is an anti-angiogenic agent that is commonly used in the treatment of breast cancer." (PMID 37389685, 2023). "In the case of coadministration of EGF, these agents exerted a lower inhibition capacity on breast cancer cell proliferation." (PMID 37575061, 2023). "EGF was shown to induce epithelial-mesenchymal transition (EMT) in EGFR-expressing human breast carcinoma cells." (PMID 36960065, 2023). "EGFR-TKI monotherapy has been utilized for EGFR mutant lung cancer, and EGF monoclonal antibodies, together with chemotherapy, have been used for breast cancer, gastric cancer, and colon cancer, among others." (PMID 37332342, 2023). "We have previously shown that in hormone-dependent breast cancer cells, epidermal growth factor (EGF) activates the PLCγ-IP3 pathway and increases the concentration of intracellular calcium which in turn interacts with and activates ERα." (PMID 38131032, 2023).
breast carcinoma (continued). "Tumor tissue derived organoids and snap frozen tissues were analyzed for BRCA1, BRCA2, ER, PR and HER2 in breast cancer, Tal2, EGF, ILF3, UBI2I, BRCA1 and BRCA2 in ovarian cancer." (PMID 37479967, 2023). "We stimulated ER+ breast cancer cells with EGF and observed a significant increase in PDE4D levels at both mRNA and protein levels." (PMID 37914699, 2023). "TG, an ER stress inducer, suppresses the proliferation of breast cancer cells, and the combined treatment of TG with the engineered fusion protein (epidermal growth factor-proteolytic A subunit) enhances its antiproliferative effect." (PMID 36835397, 2023). "Transforming Growth Factor (TGF) and Epidermal Growth Factor (EGF) signalling can trigger breast cancer tumour motility." (PMID 38097683, 2023). "In breast cancer, the inhibition of the epidermal growth factor (EGF), nuclear factor kappa B (NF-kB), ERK/Akt, and MMP 2 and 9 signaling pathways due to ECS activation results in anti-proliferative effects." (PMID 36831374, 2023). "Fascinatingly, CSF1 and EGF establish a feedback paracrine loop between CSCs and TAMs, where CSF1 recruited TAMs shed a higher amount of EGF leading to stimulation of STAT3/SOX2 pathway in breast cancer cells." (PMID 38035101, 2023). "For example, mitochondrial translocation of EGFR occurs in breast cancer cells in response to EGF stimulation, which subsequently induces the phosphorylation of cytochrome c oxidase subunit II (Cox II) in the mitochondria and enhances cancer cell survival." (PMID 37461111, 2023). "The activation of TGF‐β and EGF signaling pathways plays a critical role in cancer metastasis and proliferation, respectively, where LY6K is required for TGF‐β‐ and EGF‐induced metastasis in breast cancer and glioblastoma." (PMID 37076981, 2023). "Another proposed model of breast cancer progression involves a three-way-relationship between oestrogen, S1P and EGF." (PMID 37038210, 2023). "The EGF signaling pathway also induces the infiltration of breast cancer cells into blood vessels, thereby promoting blood vessel metastasis." (PMID 37445965, 2023). "Thereafter, we have demonstrated that the uptake of general ligand of scavenging receptors acLDL and tumor-specific ligand EGF in TAMs of breast cancer was significantly decreased in the presence of cisplatin." (PMID 36960065, 2023). "EGFR-activated AKT inhibits GSK3β activity via Ser9 phosphorylation, suppresses EGF signaling in basal-like breast cancer (BLBC) cells, reduces PD-L1 stability, and decreases cancer cell immune escape, thereby demonstrating a therapeutic benefit." (PMID 37554324, 2023). "Another study has shown that Rac1-modulated macropinocytosis is also required for the EGF-induced internalization of E-cadherin in breast carcinoma." (PMID 37132654, 2023). "Elbaz and colleagues reported that CBD inhibits EGF-induced breast cancer cell proliferation and, interestingly, reduces MMP9 secretion and lung metastasis in vivo." (PMID 37686233, 2023). "It was reported that ECM1 induces tumor growth by promoting angiogenesis or enhancing the EGF signaling in the breast cancer." (PMID 36765767, 2023). "We exposed MDA-MB-231 cells to gradients of EGF, another driver of cell migration in breast cancer metastasis." (PMID 36829763, 2023). "In contrast, activated SSTRs suppressed tumour growth and also block EGF-induced cell proliferation and ErbBs complex formation in breast cancer cells." (PMID 38203605, 2023). "In BCN, EGF-EGFR pair was identified as the key regulator (EGF interactions = 152, EGFR interactions = 358, total number of interactions = 510), which has been known to be associated with poor prognosis in breast cancer." (PMID 37566630, 2023). "FTH1 nanoparticles coated with EGF have been successfully applied to breast cancer in vitro and in vivo." (PMID 38025726, 2023).
breast carcinoma (continued). "Although EGF and its receptors have received more attention in breast cancer research to date, our findings highlight the key role played by FGFs and their receptors in promoting drug resistance to tubulin polymerization inhibitors in FGFR-positive tumors." (PMID 37509496, 2023). "Cetuximab is a monoclonal antibody targeting epidermal growth factor receptor (EGFR) for inhibiting the EGF signaling pathway in breast cancer." (PMID 37900279, 2023). "Pluripotency markers OCT4, SOX2 with cancer markers BRCA1, BRCA2, ER, PR and HER2 in breast cancer iPSCs; Tal2, EGF, ILF3, UBI2I, BRCA1 and BRCA2 in ovarian cancer iPSCs were analyzed." (PMID 37479967, 2023). "In this study for the first time we show that stabilin-1 is a specific scavenger receptor for EGF, a growth factor critical for progression of breast cancer." (PMID 36960065, 2023). "Chemotaxis assays showed that reduced expression of G3BP1 significantly inhibited the epidermal growth factor (EGF)-induced chemotactic motility of breast cancer cells." (PMID 36330442, 2022). "Meanwhile, ERBB2 (erb-b2 receptor tyrosine kinase 2) is a member of the epidermal growth factor (EGF) receptor family genes encoding for well-known HER2 protein, which is known to play an essential role in breast cancer progression and treatment selection." (PMID 36009413, 2022). "In breast cancers, estrogen has been shown to promote the release of heparan-bound epidermal growth factor (HB-EGF), thereby inducing activation of the EGF receptor and downstream ERK signaling." (PMID 36497371, 2022). "Epidermal growth factor (EGF)-induced EMT in human breast cancer cells revealed an upregulation of P2X5R mRNA, resulting in an increase in ATP-mediated Ca2+ signaling." (PMID 35350689, 2022). "Further, exploration of the role of G3BP1 in cellular signaling processes, showed the G3BP1 knockdown significantly inhibited the phosphorylation of Akt 473, integrin β1, and cofilin in EGF-induced breast cancer MDA-MB-231 cells as verified by western blot." (PMID 36330442, 2022). "Another mechanism by which ARF1 regulates the migration of highly invasive breast cancer cells consists of controlling an EGF-dependent assembly of focal adhesions." (PMID 35805075, 2022). "We found, for both a breast cancer and pancreatic cancer cell line, that cells migrated in the direction of an epidermal growth factor (EGF) gradient and a transforming growth factor β (TGF-β) gradient when each gradient was presented individually." (PMID 36450797, 2022). "The results showed that the reduction of G3BP1 expression significantly inhibited EGF-induced actin polymerization in breast cancer cells." (PMID 36330442, 2022). "Mechanistically, ERK5 inhibition of EC cells resulted in impairment of EGF-induced c-Jun expression and AP-1 transcriptional activity, as reported for other ERK5i in cancer types, such as breast cancer and hepatocellular carcinoma." (PMID 36123565, 2022). "In breast cancer cells, the role of EGF in promoting migratory behavior was shown to be mediated substantially through functional VGSC expression, i.e., TTX suppressed the increase in cellular migration induced by EGF dose dependently." (PMID 35681682, 2022). "EGF induces the infiltration of breast cancer cells into the blood vessels, leading blood vessel metastasis." (PMID 34914196, 2022). "TAMs are able to sustain tumor cell growth through the production of growth factors such as epidermal growth factor (EGF), which induce breast cancer cell proliferation." (PMID 36359283, 2022). "ERBB2 (HER2) is overexpressed in 15-20% of breast cancer in response to EGF activation, and plays a major role in EMT." (PMID 36034422, 2022). "Similar to TcdB treatment, TcdBNXN-treated cells also exhibited a strong upregulation in “HER-2 Signaling in Breast cancer” along with a strong upregulation in “EGF Signaling”." (PMID 35457076, 2022).